MIR369 (microRNA 369)
Synonyms: hsa-mir-369; MIR369-3; MIRN369; MIRN369-3; mir-369
Gene: MicroRNA gene on chromosome 14 (101,065,598 to 101,065,667, forward strand). Ensembl gene ENSG00000199025.
Gene Ontology:
Biological process: miRNA-mediated post-transcriptional gene silencing
Cellular component: RISC complex
Homologues: Orthologues: chimpanzee ptr-mir-369 (100% identical), guinea pig MIR369 (96% identical). Paralogues in human: MIR154 (69% identical), MIR323A (67% identical), MIR381 (66% identical), MIR323B (64% identical), MIR410 (64% identical), MIR496 (64% identical), MIR494 (63% identical), MIR539 (63% identical), MIR1185-1 (61% identical), MIR382 (61% identical), MIR377 (60% identical), MIR487A (60% identical), and 4 more.